CRP (C-reactive protein)
Diseases named in the same sentence as CRP in open-access papers (continued):
Sharing a sentence is not in itself a finding about the gene and the disease.
COVID-19 (continued). "Of the other routinely used biomarkers, only CRP proved to be a predictor of the severity of COVID-19 in our cohort." (PMID 39518479, 2024). "Inflammatory biomarkers such as C-reactive protein (CRP), neutrophil-to-lymphocyte ratio (NLR), and interleukin-6 (IL-6) have been reported to be associated with the clinical course of COVID-19 during hospitalisation." (PMID 38982551, 2024). "Equally significant is the elevated inflammatory marker C-reactive protein (CRP) observed in patients with COVID-19, surpassing levels detected in patients with myocarditis." (PMID 38303719, 2024). "The results of statistical analysis using the independent t test between CRP and COVID-19 severity in pregnant women showed significant difference between CRP and COVID-19 severity in pregnant women (<0.001)." (PMID 38905361, 2024). "Age, the requirement of MV, leukocytosis, neutrophilia, and an increase in CRP, NLR, and CLR showed a statistically significant association with the mortality of ICU patients with COVID-19 in the univariate analysis." (PMID 38421951, 2024). "A retrospective study showed CRP measured both on admission and during the course of the disease in patients with COVID-19 was helpful for guiding therapy." (PMID 38698064, 2024). "For example, elevated levels of inflammatory markers, such as CRP and interleukin-6 (IL-6), have been observed in cancer patients with COVID-19, indicating a heightened inflammatory response." (PMID 39655133, 2024). "In severe COVID-19 patients, all CE species negatively correlated with CRP, 13 CE species with procalcitonin, 9 with IL-6, and 10 with ferritin." (PMID 39051245, 2024). "The concentration of C-reactive protein, transmembrane serine protease 2, and klotho protein were significantly greater in the urine of COVID-19-positive participants." (PMID 39861814, 2024). "In patients infected with COVID-19, a high CRP of ≥40 mg/L carried a poor prognosis with a lower cut-off of ≥35 mg/L in the elderly, particularly when combined with lymphopenia and coagulopathy marked by elevated D-dimer." (PMID 39009040, 2024). "We analyzed correlations between neopterin levels, CRP, albumin levels, and the CRP/albumin ratio in severe COVID-19 patients." (PMID 39058886, 2024). "An increased C reactive protein (CRP) plasma concentration correlates with the severity and poor prognosis of COVID-19." (PMID 38474287, 2024). "In COVID-19 positive cases, CRP and ferritin levels were significantly elevated compared to negative cases (CRP: 120 mg/L vs. 10 mg/L; ferritin: 600 ng/mL vs. 150 ng/mL)." (PMID 39767161, 2024). "CRP is an acute-phase protein produced by the liver in response to inflammatory cytokines, with levels markedly elevated in patients with COVID-19, correlating positively with disease severity and mortality." (PMID 39661669, 2024). "Elevated CRP levels were related with higher risk of thrombosis, whereas increased LDH indicated the presence of tissue damage in COVID-19 patients." (PMID 38216918, 2024). "Correlation analyses among these inflammatory biomarkers showed a correlation between neopterin levels and CRP and albumin levels in COVID-19 patients." (PMID 39058886, 2024). "Antimicrobials were more prevalent in individuals with higher WBC levels, increased CRP levels, heightened COVID-19 severity, and those requiring supplemental oxygen." (PMID 38543674, 2024). "Of the peripheral blood parameters, only CRP had some value, i.e. AUC = 0.77 for the differentiation between COVID-19 and dCtrl (viral)." (PMID 38961383, 2024). "In agreement, the CATALYST trial confirmed that Infliximab did not demonstrate any evidence of reducing inflammation, as indicated by CRP concentration, in COVID-19 patients who were admitted to hospital." (PMID 39459457, 2024). "Patients treated at the ICU were more likely to have cardiovascular and respiratory symptoms, as well as a history of symptomatic COVID-19, higher CRP, PCT, BNP and lower albumin levels." (PMID 39596959, 2024).
COVID-19 (continued). "Univariable analysis revealed that elevated LDH; CRP; age; and high expression of CD39+CD45+, TIM3+CD39+CD4+CD45+, and TIM3+CD39+CD8+CD3+CD4+ cells were significantly associated with severe COVID-19 according to the WHO clinical progression scale." (PMID 38793691, 2024). "Specifically, we will delve deeper into the differences in LDH, CRP, and D-Di levels among COVID-19 patients who are vaccinated and unvaccinated, as well as those with normal and compromised immune statuses at the time of hospital admission." (PMID 39712749, 2024). "In COVID-19, severely ill patients have significantly lower levels of SIRT3, and its levels are negatively correlated with CRP and procalcitonin levels, indicating the association of serum SIRT3 levels with clinical outcomes and prognosis in COVID-19 patients." (PMID 39091611, 2024). "We also observed a significant increased odds of severe COVID-19 (WHO Clinical Progression Scale score 6 to 10) for increased concentration of CRP, IL6, IP10, IL8, IL1RA, and suPAR." (PMID 39664394, 2024). "Kaketani and Nakajima evaluated the efficacy of 5-ALA and SFC in treating COVID-19 patients with elevated C-reactive protein (CRP)." (PMID 39720526, 2024). "Age ≥ 60 years and BMI ≥ 30 kg/m2 at COVID-19 onset were associated with higher levels of IL2 and IP10, and MCP1 and CRP, respectively, when adjusting for other covariates." (PMID 39008486, 2024). "The calculated AUCs for patients with COVID-19 are presented as follows: CRP—0.743; glucose—0.742; LDH—0.713; ESR—0.605; N—0.589; Ly—0.532; N/L—0.563; PLT—0.51." (PMID 38392603, 2024). "Upon admission, a lower nutritional prognostic index and higher CRP/TTR and CRP/Albumin ratios were related to a higher probability of developing severe COVID-19." (PMID 39125329, 2024). "After adjusting the impact of CRP rs1205 polymorphism for SARS-CoV-2 variants, the COVID-19 mortality rate was correlated with CRP rs1205 TT and CT genotypes in the all three variants." (PMID 38184750, 2024). "Reactive markers such as C-reactive protein (CRP), ferritin, and interleukin-6 (IL-6) have been associated with COVID-19 severity as well as other comorbidities." (PMID 39835130, 2024). "In conclusion, these results allowed us to establish a model for predicting mortality among patients hospitalized with COVID-19 based on D-dimer laboratory biomarkers adjusted for CRP and oxygen saturation, with an adequate predictive value." (PMID 39685758, 2024). "In the bivariate Cox regression analysis, it was found that severe COVID-19 infection, chronic kidney disease, cancer status, age, hematocrit, leukocyte, NLR, D-Dimer, CRP, procalcitonin, and AST were associated with 30-day COVID-19 mortality." (PMID 38792539, 2024). "To further investigate this, we conducted a multifactorial regression analysis, which corroborated that vaccination emerged as a protective factor against the elevation of CRP and D-Di levels in COVID-19 patients in general." (PMID 39712749, 2024). "CRP levels after COVID-19 admission were significantly higher in men compared to women (107 ± 7 vs. 86 ± 7.3 mg/L, p < 0.05)." (PMID 39449074, 2024). "This case underscores the importance of integrating biomarker data, such as CRP's role in indicating COVID-19 severity, with clinical context to drive appropriate treatment decisions for complex infections." (PMID 39840216, 2024). "Interleukin-6 (IL-6) appears to be the key circulating cytokine associated with worse outcomes in COVID-19-related ARDS and predicts respiratory insufficiency significantly earlier than C-reactive protein (CRP)." (PMID 39274307, 2024). "One model composed of the most explanatory biochemical markers for mortality by COVID-19 included: low SpO2, and high levels of D-dimer, fibrinogen, CRP, urea, LDH and platelet count." (PMID 38500972, 2024). "CRP is another inflammatory marker elevated in both bacterial and viral infections, including COVID-19." (PMID 39840216, 2024).
COVID-19 (continued). "We recommend that the levels of CRP should be measured in combination with disease’s comorbidities to diagnose and predict COVID-19 outcome among pregnant women." (PMID 38905361, 2024). "The MII is the product of NLR and CRP, which have been considered biomarkers of lethal outcomes in COVID-19." (PMID 38298278, 2024). "In patients with COVID-19, plasma IL-34 levels correlated positively with CRP (r = 0.636, p = 0.029)." (PMID 38626032, 2024). "An earlier study has shown that CRP can be used as a prognostic indicator of COVID-19 among hospitalized patients, as it linearly increases and peaks on the 5th day of infection." (PMID 38282651, 2024). "We found that the NfL levels are significantly predicted by a panel of circulating cytokines/chemokines, including CRP, IL-4, IL-8, IL-9, Eotaxin, and MIP-1ß, which are highly up-regulated during COVID-19 and are associated with clinical outcomes." (PMID 39125829, 2024). "Patients who still had positive CRKP OX-48-like strain microbial cultures were of higher female %, inotropes receival, WBC—neutrophil—CRP counts, fever experiences, and COVID-19 comorbidity." (PMID 38534700, 2024). "A previous study demonstrated that significant reductions in HRV preceded elevations in C-reactive protein levels within 72 h in COVID-19 patients." (PMID 39732768, 2024). "Some well-known biomarkers include glycated haemoglobin (HbA1c) for diagnosis of diabetes, procalcitonin (PCT) and C-reactive protein (CRP) for COVID-19, and prostate-specific-antigen (PSA) for cancer." (PMID 39336736, 2024). "Another study included patients with much lower CRP than ours, indicating a less acute COVID-19 inflammation." (PMID 38350878, 2024). "On the other hand, COVID-19/TB patients had higher levels of C-reactive protein and lower hemoglobin levels, the latter variable was independently associated with COVID-19/TB." (PMID 39536219, 2024). "Our model suggested that the CRP to albumin ratio (CAR) is the most important determinant of COVID-19 severity." (PMID 38690475, 2024). "C-reactive protein, CPK, D dimer, and LDH were reported by multiple studies to be associated with the severity of illness in patients with COVID-19." (PMID 38515170, 2024). "In this proof-of-concept study, we evaluated the effect of dornase alfa on inflammation, as measured by the impact on circulating CRP in patients with COVID-19, compared with best available care (BAC)." (PMID 39009040, 2024). "In the case of patients diagnosed with COVID-19 in the year 2020, descriptive statistics indicated significant changes in the lymphocyte and neutrophil counts, as well as elevated values for CRP and LDH in severe forms of SARS-CoV−2 infection." (PMID 38392603, 2024). "Patients with severe COVID-19 had significantly higher CRP and creatinine and a longer duration of INR and hospital stay compared to patients in the moderate group (p < 0.05)." (PMID 39408623, 2024). "The results of their study showed that: before the start of general vaccination, most COVID-19 patients had a decrease in lymphocytes and an increase in CRP, but after the start of vaccination, these results reversed." (PMID 38741059, 2024). "Our study rigorously assessed the beneficial effects of vaccination on key clinical biomarkers (LDH, CRP, and D-Di) among COVID-19 patients, spanning a diverse range of immune statuses." (PMID 39712749, 2024). "The statistical significance analysis indicates that barring CRP levels in patients with COVID-19 and myocarditis, all other examined indicators exhibited statistically significant differences between the groups." (PMID 38303719, 2024). "Studies have shown that high CRP levels in COVID-19 cases can correlate with disease severity, reflecting the level of systemic inflammation rather than indicating a bacterial cause." (PMID 39840216, 2024).
COVID-19 (continued). "In this study, although the increased fibrinogen levels were not statistically significant, the WBC, neutrophil, D-dimer, CRP, urea, and ferritin levels increased in COVID-19 patients with lung involvement." (PMID 39309472, 2024). "Following the outbreak of the COVID-19 pandemic, IL-6, CRP, and D-dimer have been used as potential indicators to assess the intensity and prognosis of COVID-19 illness." (PMID 39759701, 2024). "CRP, IL6 and IP10 had the most robust association with both hospitalization and severe COVID-19, with CRP having the highest discriminatory capacity with hospitalization, and IL6 for severe COVID-19." (PMID 39664394, 2024). "Univariate Logistic regression showed that high CRP levels were found to be an unfavorable predictor of COVID-19 outcomes (OR = 17.9, 95%CI: 7.3, 43.6; P < .001)." (PMID 38215120, 2024). "Elevated levels of inflammatory markers, such as C-reactive protein (CRP), interleukin (IL)-6, and procalcitonin, have been associated with disease severity and poor outcomes in COVID-19 patients." (PMID 38800147, 2024). "Of note, although troponin and CRP levels were available in all 43 COVID-19 patients during their hospitalization, NT-proBNP levels were not available in 10 of the 43 COVID-19 patients." (PMID 39197405, 2024). "Extensive clinical studies have confirmed that increased CRP and D-dimer levels and decreased lymphocyte counts are reliable indicators of severe/critical COVID-19 and poor outcomes." (PMID 38462559, 2024). "As reported by other studies, COVID-19-infected pregnant women had elevated neutrophils and CRP and reduced lymphocytes correlating with severity." (PMID 39659767, 2024). "In the miRNAs with differing levels in COVID-19 patients and controls, miR-145-5p correlated with both CRP and fibrinogen (p < 0.05)." (PMID 39237986, 2024). "Retrospective studies have consistently demonstrated a positive correlation between CRP levels and COVID-19 severity, further establishing its role in predicting thrombosis risk." (PMID 39661669, 2024). "Studies have demonstrated a connection between the early initiation of Anakinra therapy in hospitalized COVID-19 patients and the positive dynamics of examined biomarkers, including the reduction in CRP, ferritin, D-dimer, and NLR." (PMID 39767597, 2024). "PCT and CRP were measured, and reverse transcriptase-polymerase chain reaction (RT-PCR) was employed for the detection of COVID-19 nucleic acid." (PMID 38172766, 2024). "these two parameters are typical for COVID-19 in co-infected patients aged over 65 years, showing low saturation (mean SpO2: 89.5%) and high mean CRP levels (mean CRP: 78.1 mg/L)." (PMID 39457522, 2024). "Baseline characteristics of 403 COVID-19 patients included sex and age; biomarkers, measured throughout the follow-up, included lymphocytes, neutrophils, ferritin, C-reactive protein, glucose, and LDH." (PMID 38541668, 2024). "An increase in vitamins A and E, zinc, and selenium levels was observed over time, concomitant with a decrease in CRP while patients were recovering from their COVID-19." (PMID 38337670, 2024). "Inflammatory markers can be used to predict the prognosis of COVID-19 patients.Early studies have reported the impact of C-reactive protein (CRP), procalcitonin (PCT), erythrocyte sedimentation rate (ESR), serum ferritin, IL-6 on the severity of COVID-19." (PMID 38671532, 2024). "The findings of the present study showed that the laboratory results of most of the patients hospitalized in the care units for corona patients before the start of general vaccination of COVID-19 included positive CRP and a decrease in lymphocytes." (PMID 38741059, 2024). "Serum neopterin, C-reactive protein (CRP), albumin levels, and complete blood count were determined in 39 patients with severe COVID-19 and 30 healthy individuals." (PMID 39058886, 2024).
COVID-19 (continued). "The potential role of the inflammatory pathway in post-COVID-19 complaints is depicted by an increase in inflammatory markers, such as IL-6, fibrinogen, neutrophils, and C-reactive protein (CRP), in individuals with post-COVID-19 condition." (PMID 39056056, 2024). "In our cohort, CRP and ferritin were identified as predictors of the necessity for advanced respiratory support in COVID-19 patients (p=0.024 and p<0.001, respectively)." (PMID 39149665, 2024). "Laboratory tests showed increased values of markers for severe COVID-19, including CRP, D-dimer, and ferritin." (PMID 39070405, 2024). "It appears that the level of IL-10 is directly proportional to Gal-1, especially in stage III of COVID-19 and to CRP." (PMID 38540252, 2024). "Age, high-sensitivity CRP level, lymphocyte count, and D-dimer level among COVID-19 patients at admission were found to be informative of the outcomes and aided our model building." (PMID 38618472, 2024). "Elevated levels of CRP, WBC, and ferritin were linked to mortality in various diseases, including COVID-19." (PMID 39458141, 2024). "Subsequently, this result was followed by two inflammatory markers in COVID-19 patients: C-reactive protein and Interleukin-6." (PMID 38702342, 2024). "In the study comprising 275 patients diagnosed with COVID-19, patients exhibiting a C-reactive protein/albumin ratio (CAR) between 1.56 and 11.19 demonstrated an eight-fold increased risk of mortality relative to those presenting with a CAR below 0.29." (PMID 39164612, 2024). "ROC analysis further validated and identified specific cut-off values for the age (72.5 years), INR (1.46 s), creatinine (78.0 μmol/L), DNA damage (9.72%), and CRP (50.0 mg/L) as significant predictors of severe COVID-19, highlighting their clinical relevance." (PMID 39408623, 2024). "On one hand, as an ARB, telmisartan rapidly and continuously reduces the level of plasma C-reactive protein in hospitalized COVID-19 patients and telmisartan treatment can shorten the hospitalization time of sufferers." (PMID 39444690, 2024). "Clinical diagnosis and severity assessment of community-acquired pneumonia and COVID-19 are based on serum CRP levels." (PMID 38184750, 2024). "Patients who have developed moderate–severe forms of COVID-19 showed an increased level of CRP from the early stages of the disease, which can be correlated with the magnitude of the imaging changes." (PMID 38392603, 2024). "Another large study from Turkey compared CRP levels of hospitalized COVID-19 patients with severe or critical disease in the first and second waves, finding significantly higher CRP levels in the second wave." (PMID 38699405, 2024). "Cytokines are messenger molecules of the immune system, including IL-6, IFN-α, IL-1β, IL-8, IL-10, IFN-γ, TNF-a, and C-reactive protein (CRP), and as such, they are closely related to the worst outcomes of COVID-19." (PMID 38012459, 2024). "Although elevated CRP has been observed in COVID-19 patients, CRP was excluded from the model analysis due to high missing value (>10%)." (PMID 38774116, 2024). "Urinary nitric oxide levels were significantly greater in the COVID-19-negative participant group while urinary C-reactive protein (CRP) levels were significantly greater in the COVID-19-positive participant group." (PMID 39861814, 2024). "From a statistical point of view, sensitive markers with a diagnostic role in COVID-19 (LDH, Glucose, CRP) and in PCI (Ly count, CRP, ESR and glucose) were highlighted." (PMID 38392603, 2024). "It is worth noting that increased levels of inflammatory parameters including PCT and CRP were significantly more common among patients with COVID-19 and DKA or HHS." (PMID 38455656, 2024). "CRP is an important inflammatory marker of COVID-19 patients, and elevated CRP levels indicate systemic inflammatory response of COVID-19 patients, and also a risk factor for severe or critical cases." (PMID 38605874, 2024).